CYP1B1 (cytochrome P450 family 1 subfamily B member 1)
Diseases named in the same sentence as CYP1B1 in open-access papers (continued):
Sharing a sentence is not in itself a finding about the gene and the disease.
colorectal cancer (22 papers, 2007 to 2026). A primary or metastatic malignant neoplasm that affects the colon or rectum. "To date, a number of molecular epidemiological studies have been done to evaluate the association between CYP1A2*F, CYP1B1 Leu432Val, Asn453Ser, and Arg48Gly polymorphisms and colorectal cancer risk in diverse populations." (PMID 25115775, 2014). "The purpose of this study is to evaluate the role of CYP1A2*F, CYP1B1 Leu432Val, Asn453Ser, and Arg48Gly genotypes in colorectal cancer susceptibility." (PMID 25115775, 2014). "A number of epidemiological studies have evaluated the association between CYP1A2*F, CYP1B1 Leu432Val, Asn453Ser, and Arg48Gly polymorphisms and colorectal cancer risk, but the results remain inconclusive." (PMID 25115775, 2014). "The previous published data on the association between CYP1A2*F (rs762551), CYP1B1 Leu432Val (rs1056836), Asn453Ser (rs180040), and Arg48Gly (rs10012) polymorphisms and colorectal cancer risk remained controversial." (PMID 25115775, 2014). "As part of a major initiative to identify major cancer susceptibility genes for colorectal cancer, we investigated three common variants in the CYP1B1 gene that individually confer a difference in the activity of the encoded protein." (PMID 20701755, 2010). "Genetic variants within the CYP1B1 that are associated with altered function appear to influence susceptibility to a colorectal cancer in Poland." (PMID 20701755, 2010). "This study examines the potential influence of CYP1B1 genetic variants alone, and in combination, on colorectal cancer risk." (PMID 20701755, 2010). "Moreover, several studies have explored the association between CYP1B1 polymorphisms—Leu432Val (rs1056836), Asn453Ser (rs1800440), and Arg48Gly (rs10012)—and colorectal cancer risk, although findings remain inconclusive." (PMID 41009721, 2025). "Results of meta-analysis for CYP1A2 and CYP1B1 polymorphisms on colorectal cancer risk." (PMID 25115775, 2014). "Therefore, we performed a comprehensive meta-analysis by including the most recent and relevant articles to identify statistical evidence of the association between CYP1A2*F, CYP1B1 Leu432Val, Asn453Ser, and Arg48Gly polymorphisms and risk of colorectal cancer that have been investigated." (PMID 25115775, 2014). "CYP1B1 contributes to colorectal cancer (CRC) resistance to ferroptosis, with its metabolite, 20-HETE, mediating this resistance." (PMID 41158511, 2025). "In colorectal cancer cells, CYP1B1 modulates the cell cycle by affecting the expression of the PCNA and FEN1 genes, ultimately promoting proliferation." (PMID 40989158, 2025). "In vitro experiments found that the CYP1B1 expression was significantly correlated with B7-H3 expression in colorectal cancer." (PMID 36428734, 2022). "This cytokine can manipulate CYP1B1 expression and can induce the activation of dietary carcinogens and DNA damage that can trigger colorectal cancer progression." (PMID 32626511, 2020). "Examples are Phortress, a synthetic CYP1A1 activated prodrug, currently undergoing phase-I trial, with potent activity against breast and colorectal cancer and resveratrol, a CYP1B1 activated cancer-preventative prodrug." (PMID 26580399, 2015). "We noticed that 3 previous meta-analysis had been reported on the colorectal cancer risk with CYP1A2*F, CYP1B1 Leu432Val, and Asn453Ser polymorphisms." (PMID 25115775, 2014). "Moreover, further studies estimating the effect of gene–gene and gene–environment interactions may eventually lead to our better, comprehensive understanding of the association between the CYP1A2*F, CYP1B1 Leu432Val, Asn453Ser, and Arg48Gly polymorphisms and colorectal cancer risk." (PMID 25115775, 2014). "Our objective was to measure the interactions between common polymorphisms of P450 (CYP1A2, CYP1B1, CYP2E1), GSTM1 and T1, SULT1A1 and cigarette smoking in colorectal cancer (CRC)." (PMID 17603900, 2007). "CYP1B1 is also a potential target for anti-PD-1 treatment of colorectal cancer." (PMID 40989158, 2025).
colorectal cancer (continued). "In addition, CYP1B1 has been shown to decrease the efficacy of anti-PD-1 therapy in colorectal cancer by preventing ferroptosis through the degradation of ACSL4." (PMID 40435846, 2025). "In summary, this meta-analysis indicates that CYP1A2*F, CYP1B1 Leu432Val, Asn453Ser, and Arg48Gly polymorphisms do not support an association with colorectal cancer, and further studies are needed to investigate the association." (PMID 25115775, 2014). "The results of our meta-analysis supported the negative association between CYP1A2*F, CYP1B1 Leu432Val, Asn453Ser, and Arg48Gly polymorphisms and colorectal cancer risk." (PMID 25115775, 2014). "The report also concluded even though no unequivocal findings were identified the role of CYP1B1 in colorectal cancer risk could not be ruled out, especially in light of histopathological evidence indicating that CYP1B1 is over-expressed in colorectal cancers." (PMID 20701755, 2010). "CpG methylation of the CYP1B1 promoter region epigenetically regulates CYP1B1 expression during the development of some colorectal cancers, and it is likely that cancers with aberrant CYP1B1 expression might show altered response to procarcinogen metabolism and chemotherapy." (PMID 26703582, 2015). "For example, in colorectal cancer (CRC), B7‐H3 inhibits ubiquitination of CYP1B1, This stabilises CYP1B1 expression and thereby enhances chemoresistance." (PMID 41537447, 2026). "In our investigation, RT-q PCR was utilized to ascertain the expression levels of C5AR1, APOE, CYP1B1, and SPP1 in a standard colon cell line and three colorectal cancer cell lines." (PMID 39494300, 2024). "Cytochrome P450 1B1 (CYP1B1), promotes ACLS4 ubiquitination and degradation in colorectal cancer." (PMID 38962305, 2024). "Moreover, elevated levels of the pro-inflammatory cytokine interleukin-6 also have effects on CYP1B1 expression in HCT116 and SW480 colorectal cancer cell lines." (PMID 32626511, 2020). "In summary, this study first unveils the crucial role of Calycosin and the CYP1B1-AKT/SP1-GPX4 regulatory axis in CRC ferroptosis, providing novel theoretical foundations for targeted therapy using traditional Chinese medicine-derived small molecules against colorectal cancer." (PMID 41493849, 2026).
Hypertension (22 papers, 2013 to 2025). The presence of chronic increased pressure in the systemic arterial system. "The hypertension-associated genes Nos1 and Abcc1 are downregulated in the hypothalamus of both rat strains, and Cyp1b1 and Fos are ISIAH-specific DEGs associated with hypertension." (PMID 39594444, 2024). "Among the DEGs that most significantly changed the transcription level only in the hypothalamus of hypertensive ISIAH rats, two genes (Cyp1b1 and Fos) are associated with hypertension." (PMID 39594444, 2024). "The ISIAH-specific response to stress associated with hypertension is represented by the Cyp1b1 and Fos genes." (PMID 39594444, 2024). "CYP1B1, transcriptionally inducible by AhR activation, is expressed in cardiovascular tissues and contributes to the development of hypertension and neointimal growth caused by vascular injury." (PMID 35739584, 2022). "Cytochrome P-4501B1 (CYP1B1) induces reactive oxygen species (ROS) to cause inflammation, cardiovascular hypertrophy and hypertension-related endothelial dysfunction, which is mediated by the activation of ERK1/2 and c-SRC signalling pathways." (PMID 34040073, 2021). "Protection against the increase in vascular reactivity, endothelial dysfunction, and ROS production associated with hypertension in female mice was found to be due to the CYP1B1-17β-estradiol generated metabolite 2-methoxyestradiol." (PMID 31948482, 2020). "Renal dysfunction and inflammation associated with angiotensin II-induced hypertension of the mouse model are cyp1b1 dependent." (PMID 24223173, 2013). "Similarly, Malik and colleagues have demonstrated an important role of CYP1B1 in hypertension and hypertension-associated pathophysiology." (PMID 33185690, 2020). "Previously, we demonstrated that the protective effect of 17-β estradiol against Ang II-induced hypertension and associated cardiovascular and renal pathophysiological changes are mediated most likely by its metabolite, 2-methoxyestradiol generated by CYP1B1 in female mice." (PMID 31948482, 2020). "It is known that inhibitors of CYP1B1 (which produces cardiotoxic metabolites), e.g., resveratrol (known for its antioxidant and cardioprotective effects) can be therapeutic agents for hypertension." (PMID 39457686, 2024). "In vivo administration of 2ME2 blunts Ang II-induced hypertension in Cyp1b1-null mice and deoxycorticosterone acetate salt-induced hypertension in Wistar rats." (PMID 35586713, 2022). "An animal study has shown that the pathogenesis of hypertension in ApoE(−/−)/Cyp1b1(+/+) mice fed a high-fat diet is most likely due to oxidative stress caused by CYP1B1, as well as increased plasma lipid levels." (PMID 36158751, 2022). "We and others have demonstrated a significant role of CYP1B1 in the pathogenesis of cardiovascular diseases, most remarkably in cardiac hypertrophy and hypertension." (PMID 33185690, 2020). "The detrimental effects of CYP1B1 in male rodents have been attributed to CYP1B1-mediated production of 6β-hydroxytestosterone which was shown to exacerbate angiotensin II-induced hypertension, renal dysfunction, and vascular changes." (PMID 33185690, 2020). "Aside from their potential chemopreventive role in cancer, flavonoids and polyphenolic compounds have also been shown to prevent various other diseases such as obesity, hypertension, and atherosclerosis, possibly via CYP1B1 inhibition." (PMID 33185690, 2020). "Of particular interest in the current study, CYP1B1 has been reported to contribute to the development of cardiovascular diseases for example ischemic heart diseases, hypertension, atherosclerosis, cardiac hypertrophy, and heart failure." (PMID 29426916, 2018). "Inhibition of CYP1B1 in the two previous studies conferred significant protection against both DOX-induced cardiotoxicity and hypertension-associated cardiomyopathy." (PMID 28078076, 2017).
Hypertension (continued). "Different studies had reported the essential roles of CYP1B1 in different diseases like metabolism diseases, hypertension, renal insufficiency, and cancers, thus, CYP1B1 was considered as potential effective biological target for the treatment of a variety diseases." (PMID 35223859, 2022). "Furthermore, CYP1B1 has been shown to contribute to the development of atherosclerosis, hypertension, and angiotensin II-induced aortic aneurysm in male apolipoprotein E-deficient mice." (PMID 33185690, 2020). "However, in contrast, Ang II-induced hypertension and cardiac and renal pathological changes that were minimized in castrated or Cyp1b1−/− mice were restored by treatment with testosterone-CYP1B1 generated metabolite 6β-hydroxytestosterone (6β-OHT)." (PMID 31948482, 2020). "Hence, deregulation of eNOS signaling and endothelial dysfunction in hypertensive disorders, associated with elevated 20-HETE levels, could be reduced via potent inhibition of CYP1B1 by TMS." (PMID 36297480, 2022). "Moreover, we showed that Ang II stimulates the production of 6β-OHT in Cyp1b1+/+, but not Cyp1b1−/− mice, and it is required (i.e., acts as a permissive factor) for Ang II-induced hypertension and associated cardiac remodeling and renal dysfunction." (PMID 31948482, 2020). "The aim of the present work was to quantify the mRNA expression of genes CYP1A1, CYP1B1, and CYP2J3 in different regions of the heart and in the aorta and to assess a possible contribution of expression changes to the development of hypertension." (PMID 39457686, 2024). "Previously, we showed that 6β-hydroxytestosterone (6β-OHT), a cytochrome P450 1B1 (CYP1B1)-derived metabolite of testosterone, contributes to angiotensin II (Ang II)-induced hypertension in male mice." (PMID 31948482, 2020). "Incorporating CYP1B1 and the NAS/melatonin ratio into these gut-driven changes allows for a more plausible biological modelling of how stress and depression can link to hypertension and LVH." (PMID 31434333, 2019). "Similarly, central Cytochrome P450 1B1 (CYP1B1)-estradiol metabolite, 2-Methoxyestradiol, protects from neuroinflammation and hypertension in female mice." (PMID 40356772, 2025). "Unlike TMS, a well-known CYP1B1 inhibitor, 2 ME protects against Ang II-induced hypertension and oxidative stress in female mice." (PMID 29426916, 2018). "Unlike TMS, 2 ME protects against Ang II-induced hypertension and oxidative stress in Cyp1b1(−/−) female mice." (PMID 29426916, 2018).
ovarian carcinoma (22 papers, 2001 to 2025). A malignant neoplasm originating from the surface ovarian epithelium. "Polymorphisms in genes responsible forestrogen catabolism, such as CYP1B1, can alter cellular levels ofgenotoxic catechol estrogens and antiangiogenic 2-methoxyestradiol, therebyinfluencing the risk of ovarian cancer development." (PMID 41158532, 2025). "It is well known that CYP1B1 is highly expressed in ovarian cancer and is associated with poor prognosis and anticancer drug resistance." (PMID 38001897, 2023). "Concordant with previous studies, such an association was reported where CYP1B1 was markedly expressed in late clinical stages of ovarian cancers and renal cell carcinomas." (PMID 33692504, 2021). "Several polymorphism of CYP1B1 are found in many cancer types, including tobacco-related cancers; CYP1B1 is also overexpressed in ovarian cancer." (PMID 28146432, 2017). "The women with two copies of both the low-activity COMT allele plus the high-activity CYP1B1 allele demonstrated much higher values of the DNA adduct ratio, and the odds ratio for ovarian cancer was 6-fold higher compared to women with the normal-activity alleles of the enzymes." (PMID 30854528, 2017). "However no reproducible significant associations between genotype and outcome were found for CYP1B1 polymorphism in a recent study in ovarian cancer patients treated with carboplatin and taxane regimens in the Scottish Randomised Trial in Ovarian Cancer phase III trial." (PMID 20875115, 2010). "It has been reported that the high expression of CYP1B1 promotes the resistance of ovarian cancer cells and PCa cells to docetaxel." (PMID 35292057, 2022). "It has also been shown that LYAR, PDIA3, NOP14, NCALD, MTSS1 and CYP1B1 are correlated with the prognosis of ovarian cancer." (PMID 34696677, 2021). "Most primary ovarian cancers (92%) show CYP1B1 immunoreactivity, present in the cytoplasm of the tumor cells." (PMID 32626511, 2020). "Immunohistochemical investigations have confirmed CYP1B1 overexpression in a majority of ovarian cancers." (PMID 32626511, 2020). "CYP1B1 was overexpressed in the samples from primary and metastatic loci of epithelial ovarian cancers." (PMID 25516145, 2015). "Furthermore, increased CYP1B1 expression was correlated with higher drug resistance in breast and ovarian cancer cells." (PMID 38001897, 2023). "We believe that such resistance to immune checkpoint inhibitors may be mirrored in ovarian cancer and that CYP1B1 inhibitors may play a role in improving and overcoming resistance to immune checkpoint inhibitors." (PMID 38001897, 2023). "In addition, LYAR and five other genes (PDIA3, NOP14, NCALD, MTSS1, and CYP1B1) showed potential as prognostic biomarkers for radical ovarian cancer." (PMID 34696677, 2021). "Intriguingly, CYP1B1 has been shown to be overexpressed in malignant tumor tissues, particularly in hormone-responsive tissues such as prostate, breast, and ovarian cancers." (PMID 33185690, 2020). "Several studies have suggested that the CYP1B1 gene may be a marker for ovarian cancer and a possible target for intervention." (PMID 24961659, 2014). "In addition, the presence of SNPs in CYP1B1 and COMT that increase both the formation of depurinating estrogen-DNA adducts and the likelihood of ovarian cancer (six-fold) supports an ER-independent mechanism of cancer initiation by estrogens." (PMID 34361004, 2021). "A gene expression profile study with whole blood cell mRNA from ovarian cancer patients revealed LYAR and other five genes (PDIA3, NOP14, NCALD, MTSS1 and CYP1B1) as potential prognostic biomarkers for curative and postoperative supportive therapies for ovarian cancer." (PMID 26413750, 2015).
primary open-angle glaucoma (21 papers, 2007 to 2025). "Few heterozygous CYP1B1 mutations were associated with the milder, primary, open-angle glaucoma phenotypes in patients from Spain, France, and India." (PMID 20057908, 2009). "Patients affected with primary congenital or open angle glaucoma carrying double heterozygous mutations, one in CYP1B1 and the other in MYOC, have previously been reported in three studies." (PMID 18385784, 2008). "The authors suggested that CYP1B1 may act as a modifier locus for MYOC in promoting open angle glaucoma." (PMID 18385784, 2008). "For example, specific genes, such as CYP1B1, which is linked to primary congenital glaucoma, and MYOC, OPTN, and TBK1, which are associated with primary open-angle glaucoma (POAG), are highlighted as critical markers for assessing genetic risk." (PMID 39840199, 2024). "In addition, CYP1B1 variants have been found in juvenile open-angle glaucoma (JOAG) and adult-onset primary open-angle glaucoma (POAG)." (PMID 40141740, 2025). "In addition to these congenital eye diseases, compound heterozygous CYP1B1 variants have also been reported in patients with JOAG, which is defined as open-angle glaucoma without anterior segment dysgenesis diagnosed between 3 and 40 years of age." (PMID 40141740, 2025). "This study was designed to evaluate the involvement of the CYP1B1, MYOC, OPTN, and OPTC genes in the etiology of adult-onset primary open-angle glaucoma (POAG) found in 251 Indian patients." (PMID 17563717, 2007).
juvenile open angle glaucoma (15 papers, 2008 to 2025). Juvenile glaucoma (JG) is a rare autosomal dominant open angle glaucoma, characterized by early onset, severe elevation of intra ocular pressure of rapid progression, leading to optic nerve excavation and, when untreated, substantial visual impairment. "Further studies declared that the CYP1B1 variant, which is reported as the variant’s conflicting interpretation of the pathogenicity, is the candidate pathogenic mutation for glaucoma 3A (GLC3A) in our case study." (PMID 36239105, 2022). "Previous studies have indicated a minor involvement of the mutations in CYP1B1 in the pathogenesis of juvenile open-angle glaucoma (JOAG) and POAG." (PMID 22509109, 2012). "Pathogenic homozygous CYP1B1 (HGNC:2597) variants are associated with Anterior segment dysgenesis 6, multiple subtypes (OMIM #617315) and Glaucoma 3A, primary open angle, congenital, juvenile, or adult onset (OMIM #231300)." (PMID 38622594, 2024). "In primary childhood glaucoma cases (n = 10), which comprised PCG and JOAG, the most common mutation was CYP1B1 (3 cases; 30%)." (PMID 35011756, 2021). "One of these studies screened the common CYP1B1 mutations in Iranian POAG patients, which found CYP1B1, as an effective cause in POAG subjects, mainly in juvenile glaucoma." (PMID 30923720, 2019). "This study was designed to analyze two candidate genes, myocilin (MYOC) and cytochrome P450 1B1 (CYP1B1), in a Chinese pedigree of juvenile glaucoma with goniodysgenesis." (PMID 19668597, 2009). "They postulate that this connection between CYP1B1 and MYOC may explain the digenic mode of inheritance seen in some cases of juvenile glaucoma." (PMID 34638643, 2021).